PTH (parathyroid hormone)
Diseases named in the same sentence as PTH in open-access papers (continued):
Sharing a sentence is not in itself a finding about the gene and the disease.
Hypocalcemia (continued). "The PTGs are essential in restoring hypocalcaemia by secretion of parathyroid hormone (PTH)." (PMID 33922173, 2021). "In addition to the operative complications, hypophosphatemia, hypocalcemia, and occurrence and progression of the hungry bone syndrome are the most severe and common complications due to sudden serum PTH reduction following parathyroidectomy." (PMID 34408941, 2021). "Secondary outcomes will be the post-operative biochemical levels of calcium and PTH, the development of clinical hypocalcemia (symptoms as reported by the patient) during post-operative hospital stay, and the ThyPRO-39 and EQ-5D-5L results at hospital discharge." (PMID 35071309, 2021). "Of note, hypomagnesemia, a described complication of gut malabsorption, may worsen SHPT by inducing hypocalcemia, low serum 1,25(OH)2D3 and impaired PTH secretion and increased skeletal PTH resistance." (PMID 34371838, 2021). "The influence of postoperative PTH seen on hypocalcemia occurrence stimulates the need for more studies focused on levels of this hormone with a view to better understand the hormonal dynamics and the processes involved in reducing post-total thyroidectomy hypocalcemia." (PMID 31492617, 2021). "PTH at 3 h after total thyroidectomy accurately predicts post-operative hypocalcemia." (PMID 34574074, 2021). "Although low PTH after surgery has been previously shown to be associated with symptomatic hypocalcemia, the routine analysis of post-thyroidectomy PTH is not universally accepted." (PMID 34574074, 2021). "As data on postoperative PTH levels were lacking we were unable to prove that postoperative hypocalcemia is caused by postoperative hypoparathyroidism." (PMID 34659111, 2021). "Furthermore, this finding supports a previous hypothesis that a sudden decrease in serum PTH concentrations after sustained elevation following parathyroidectomy results in the unopposed action of osteoblasts and massive influx of calcium into bone, thereby causing severe hypocalcemia." (PMID 33143476, 2020). "In the current study, hypocalcemia, elevated parathyroid hormone (PTH), and rickets were observed in mutant Vdr (R270L) rats and may have resulted from reduced affinity of 1,25(OH)2D3 for the variant Vdr." (PMID 32231239, 2020). "It generally progresses with hypocalcemia, hyperphosphatemia, and low-normal PTH levels." (PMID 33033457, 2020). "Early prediction of postoperative hypocalcemia is certainly desirable; however, certain surgeons have indicated that the postoperative 1-hour PTH level has equivalent reliability to the postoperative day 1 PTH levels for predicting the development of symptomatic hypocalcemia." (PMID 32802056, 2020). "As CKD progresses, the elevation of serum fibroblast growth factor 23 (FGF23) leads to suppression calcitriol production, consequently inducing hypocalcaemia and stimulating parathyroid hormone (PTH) secretion, ultimately resulting in decreased bone mineral density (BMD)." (PMID 32188054, 2020). "Furthermore, hypocalcemia leads to an endocrine feedback loop stimulating parathyroid hormone (PTH) production and secretion." (PMID 33361800, 2020). "Hypocalcemia in COVID-19 could be a direct effect of SARS-CoV-2 or could result from an imbalance in parathyroid hormone (PTH) and/or 25-hydroxyvitamin D. In general, calcium is required for virus structure formation, entry, replication, and virion release." (PMID 33490095, 2020). "The purpose of our study was to accurately investigate the effect of low vitamin D level in developing hypocalcemia, and postoperative PTH could serve as a confounder; therefore, we decided to study only patients with postoperative PTH level <15 pg/mL." (PMID 32774362, 2020). "The threshold to define vitamin D deficiency has no consensus world wide, as it can be defined variously according to population-based reference limits for serum 25(OH)VitD3 concentrations or biological indices, such as hypocalcemia, and elevated intact PTH concentrations." (PMID 32582730, 2020).
Hypocalcemia (continued). "In that study, it is shown that patients with CU have a higher rate of OP and hypocalcemia, as well as lower levels of parathyroid hormone (PTH) and vitamin D. In fact, the levels of PTH are significantly lower in patients with OP and CU, compared to patients diagnosed with OP alone." (PMID 32635380, 2020). "Insufficient PTH secretion or function results in signs and symptoms arising from hypocalcemia, which interferes with muscle contraction and nerve conduction: paresthesia, tingling sensation in the mouth, hands and feet, cramps, and tetanic muscle spasms of the hands and feet." (PMID 32751307, 2020). "PTH can also act directly on bone to increase osteoclastic reabsorption, but in the absence of adequate 1,2(OH)2D action the release of calcium and phosphorus from bone is impaired and cannot fully reverse hypocalcemia or hypophosphatemia." (PMID 32596195, 2020). "Notably, hypocalcemia can directly stimulate the production of parathyroid hormone, leading to excessive mobilization of calcium from the bone to maintain normal serum calcium levels." (PMID 33132823, 2020). "Symptoms improve with correction of hypocalcemia (calcium and vitamin D supplementation); however, PTH besides hypocalcemia may play a direct role since PTHR is expressed in various areas of the brain." (PMID 32751307, 2020). "Our logistics analysis revealed that the PTH level reduction on postoperative day 1 was an independent risk factor for transient hypocalcemia, however not preoperative Ca or PTH levels." (PMID 32802056, 2020). "When challenged with a low calcium diet, all mice had hypocalcaemia, and elevated plasma PTH concentrations and alkaline phosphatase activities, and Sox3−/Y, Sox3+/−, uc482−/Y, and uc482+/− mice had similar plasma biochemistry, compared to wild-type littermates." (PMID 31961795, 2020). "Another future perspective would be correlating the scores of IGFA with the change in intra-operative PTH measurements, since reduced PTH levels may be a predictor of post-operative symptomatic hypocalcaemia during thyroidectomy." (PMID 32267347, 2020). "The abrupt reduction in serum PTH concentration after parathyroidectomy is believed to modify the balance between bone formation and resorption, favoring bone formation with greatly increased skeletal uptake of calcium, which results in severe hypocalcemia." (PMID 33143476, 2020). "The supplementation of 60 mg/kg αT3 for 3 months did not improve the changes (hypocalcemia, elevated PTH and low bone calcium content) caused by vitamin E deficiency in female rats." (PMID 31963885, 2020). "Total thyroidectomy can be performed safely without routine Ca/PTH measurement, without routine Ca supplementation, and with no risk of long-term hypocalcaemia in patients with at least one well vascularised PG." (PMID 32267347, 2020). "In addition, the PTH-ICGT assay was found to decrease the incidence of transient hypocalcemia, as compared with direct visual inspection by experienced surgeons." (PMID 33967947, 2020). "In postoperative hypoparathyroidism, the injured parathyroid glands are unable to increase the secretion of PTH and, thus, predispose VDD patients to more severe hypocalcemia because their calcium regulation is more dependent on serum PTH levels than that of patients without vitamin D insufficiency." (PMID 32774362, 2020). "Moreover, the women receiving hormone therapy showed a blunted PTH response to the induction of EDTA‐mediated hypocalcemia." (PMID 32803112, 2020). "Laboratory tests revealed hypocalcemia (1.45 mmol/L [2.20–2.70]), hyperphosphatemia (2.74 mmol/L [0.8–1.6]), elevated serum PTH (671.9 ng/L [15.0–65.0]), decreased 24-hour urinary calcium and phosphorous (0.141 mmol and 0.846 mmol respectively, [2.5–7.5] and [2.10–8.19], respectively)." (PMID 32481259, 2020).
Hypocalcemia (continued). "In contrast, there were significantly more dogs with parathyroid-hormone dependent hypocalcemia, kidney injury, eclampsia, and critical illness in cases where ionized calcium concentrations were moderately-to-severely decreased compared to when they were only mildly decreased." (PMID 31508432, 2019). "Mild chronic hypocalcemia will trigger all mechanisms resulting in elevated PTH levels." (PMID 30927339, 2019). "Laboratory tests showed hypocalcemia and elevated serum levels of intact parathyroid hormone." (PMID 31102836, 2019). "Etelcalcetide and cinacalcet should not be coadministered, given the added risk of hypocalcemia that results from the similar mechanisms of action and effects on serum levels of PTH, calcium, and phosphorous." (PMID 30875390, 2019). "However, postoperative calcium and calcitriol replacement should be performed only when the patient develops symptoms of hypocalcemia or when calcium or PTH levels are below normal." (PMID 31340251, 2019). "Severe hypocalcaemia and high PTH level couldn’t be explained solely by marginally low (insufficient) Vitamin D level." (PMID 31856822, 2019). "There was only one patient 0.11% who required calcium and vitamin D supplement for more than six months postoperatively and follow-up till one year and was considered permanent hypocalcaemia we also did postoperative PTH levels in this patient and that was low." (PMID 30881435, 2019). "Therefore, in course of early-onset neonatal hypocalcemia, the maternal serum levels of calcium and PTH must be measured for etiological evaluation." (PMID 31320908, 2019). "Although severe hypomagnesemia is well known to cause hypocalcaemia through a combination of defective PTH secretion and some degree of PTH resistance mild hypomagnesemia is unlikely to cause isolated PTH resistance leading to such severe hypocalcaemia." (PMID 31856822, 2019). "Hypocalcemia for six or more months after surgery, with or without symptoms in the presence of a low or inappropriately normal PTH is diagnostic of permanent surgical hypoparathyroidism." (PMID 30540559, 2019). "A correlation matrix of potential auxiliary variables was created and, as no variable showed a correlation (r > 0.4), we created an imputation model using preoperative total calcium, preoperative PTH, age and postoperative hypocalcemia as the auxiliary variables." (PMID 31340251, 2019). "Since hypocalcemia stimulates PTH production and decreased levels of 1,25D results in failure to inhibit PTH synthesis, an excessive rise in PTH release often accompanied by parathyroid hyperplasia, is common in CKD patients and referred as secondary hyperparathyroidism (SHPT)." (PMID 31241466, 2019). "Epidemiologic studies found an inverse association of serum calcidiol with serum PTH but did not report data on high PTH, serum calcium, or hypocalcemia." (PMID 31374914, 2019). "Therefore, to avoid hypocalcemia, parathyroid hormone increases substantially (secondary hyperparathyroidism) and stimulates osteoclast-mediated bone degradation." (PMID 31277328, 2019). "Hypocalcemia in urethral obstruction may be due to phosphate retention secondary to obstruction, PTH resistance, or acid-base alterations." (PMID 31508432, 2019). "PTH is released upon hypocalcemia, indirectly stimulating release of calcium from bone." (PMID 30805347, 2019). "However hypocalcaemia, hyperphosphataemia and increased PTH seen in this patient favor the diagnosis of PHP." (PMID 31856822, 2019). "The PTG adapts swiftly to conditions requiring enhanced PTH secretion, such as hypocalcemia." (PMID 30927339, 2019). "Finally, it seemed quite logical for the pre- and post-operative determination of calcium and PTH for a suitable treatment of hypocalcemia." (PMID 30989072, 2019). "Both absolute and relative decrease in the level of PTH has been used to predict hypocalcemia with similar accuracy and, although both levels are similar, they may vary between institutions." (PMID 31281762, 2019).
Hypocalcemia (continued). "A low or inappropriately normal PTH despite hypocalcemia may suggest primary hypoparathyroidism or hypomagnesemia." (PMID 31320908, 2019). "Most thyroid surgeons provide calcium supplementation based on postoperative calcium, parathyroid hormone (PTH) serum levels, or presence of symptoms, whereas others routinely prescribe calcium and vitamin D supplementation after thyroidectomy to prevent hypocalcemia symptoms." (PMID 31340251, 2019). "The clinical symptoms (for instance, ossifications and brachydactyly) and abnormalities that can be detected in a laboratory (for instance, hypocalcaemia and raised levels of PTH) typically worsen during mid and late childhood and are usually unnoticed in very young children." (PMID 29959430, 2018). "Severe hypocalcemia is unlikely with a normal PTH value measured after surgery." (PMID 29694629, 2018). "Accordingly, treatment with oral calcium and active vitamin D supplementation can be used to target a higher serum level of calcium than in patients with PTH-deficient hypocalcaemia, where treatment targets the low–normal or slightly reduced range of calcium." (PMID 29959430, 2018). "Hypocalcemia in Gitelman syndrome is rare, and may be related to inhibited PTH secretion induced by hypomagnesemia." (PMID 30558554, 2018). "Classical manifestations of PHP‐1a and PHP‐1c are primary hypothyroidism without goiter, hypocalcemia with elevated PTH level, short stature due to GH deficiency, and hypogonadism." (PMID 30349702, 2018). "Treatment with active vitamin D metabolites or analogues could also be considered when levels of PTH are more than twice the upper level of normal, independently of the presence of hypocalcaemia (B+)." (PMID 29959430, 2018). "Cyp27b1–/–mice exhibit marked hypocalcemia and high PTH levels after weaning." (PMID 30281599, 2018). "On the other hand, acute hypermagnesemia (due to the excessive parenteral administration or renal insufficiency) also leads to hypocalcemia since magnesium may activate CaSRs and suppress PTH secretion." (PMID 29694629, 2018). "Further, overtreatment for hypocalcemia caused by hypoparathyroidism induces kidney dysfunction by hypercalciuria, because its standard treatment is not parathyroid hormone (PTH) replacement but supplementation of vitamin D analogs and Ca13." (PMID 30242201, 2018). "Finally, PTH on day one following the surgery was a statistically significant predictor of post-operative hypocalcemia (OR 0.96, 95% CI 0.94–0.97, p < 0.001)." (PMID 30092793, 2018). "In the intestine, under the influence of 1,25(OH)2D, synthesis of a protein binding calcium and calcium absorption are increased, in bones—calcium and phosphates (in case of hypocalcemia) are released, and in kidneys—calcium is reabsorbed with input from PTH activity." (PMID 29904370, 2018). "Both reduced calcitriol levels and hypocalcaemia stimulate the synthesis PTH." (PMID 29865146, 2018). "Of particular interest in this context is the observation of a downregulation of Gnas gene products following TDF-exposure that might translate into a degree of end-organ resistance to PTH and prevent compensation of hypocalcemia." (PMID 30687401, 2018). "The mechanisms underlying ROD include reduced renal excretion of phosphate and impaired gastrointestinal and renal reabsorption of calcium, resulting in hyperphosphatemia and hypocalcemia, subsequently stimulating production and release of parathyroid hormone (PTH)." (PMID 30155452, 2018). "Therefore, the aim of the present investigation was to study the impact of FGF23 on the Ca2+/PTH relationship in vivo under conditions of normocalcemia and hypocalcemia." (PMID 29063159, 2018). "Low levels of PTH in Ns-HypoPT and end-organ resistance to PTH in PHP leads to hypocalcemia." (PMID 29971010, 2018).
Hypocalcemia (continued). "Both hypocalcemia and 1,25D deficiency among CKD patients result in PTH secretion and PTG hyperplasia and consequently result in unbalanced bone remodeling, soft tissue/vascular calcification, and increases the risk of cardiovascular event and all-cause mortality." (PMID 30513912, 2018). "It has been postulated that hypocalcemia could be related to the calcium soaps formation and parathyroid hormone depletion." (PMID 29976140, 2018). "A final word is that the majority of patients in the study were vitamin D deficient; however, this did not increase the risk of post-thyroidectomy hypocalcemia, nor did it interfere with the predictability of PTH as a marker of post-thyroidectomy hypocalcemia." (PMID 28955671, 2017). "Post-thyroidectomy hypomagnesemia has been approved to reduce the production of PTH, decrease the affinity of PTH receptor and production of vitamin D, all of which may lead to hypocalcemia." (PMID 28545530, 2017). "Most patients present with hypocalcemia, hyperphosphatemia, and elevated levels of PTH." (PMID 27425121, 2017). "There is therefore hypocalcemia with normal or low PTH but that is maladjusted in all cases." (PMID 28122587, 2017). "In platinum-treated patients, hypocalcemia is principally related to hypomagnesemia (although severe hypermagnesemia may have the same effect) since magnesium is a required cofactor for parathyroid hormone (PTH) release." (PMID 28730291, 2017). "Biochemical studies of post-thyroidectomy patients have demonstrated that PTH levels at various times correlate with the development of symptomatic hypocalcemia, although the optimal timing remains unclear." (PMID 28955671, 2017). "Hypocalcemia can be due to decreased absorption from the gut secondary to the state of hypovitaminosis D. This may then trigger an increase in circulating parathyroid hormone." (PMID 28698728, 2017). "In our study, we also evaluated whether preoperative VDD reduces the accuracy of postoperative PTH in predicting post-thyroidectomy hypocalcemia." (PMID 29100453, 2017). "They concluded that secondary hyperparathyroidism influences the postoperative PTH level in vitamin-D-deficient patients, and hence it is not a reliable predictor for hypocalcemia in this subset of patients." (PMID 28955671, 2017). "Upon ruling out all other major etiologies for seizures, initial evaluation identified severe hypocalcemia of 5.7 mg/dl, hyperphosphatemia of 11.5 mg/dl, and inappropriately low PTH of 20.7, alongside normal albumin, magnesium, potassium, chloride, blood gases, and vitamin D levels." (PMID 28444561, 2017). "Unlike patients with PHPT, patients with SHPT have a compensatory PTH secretion for hypocalcaemia." (PMID 29233127, 2017). "Hypomagnesaemia also produces impaired parathyroid hormone secretion, which may lead to hypocalcaemia." (PMID 28103324, 2017). "This is in contrast with the findings of other researchers who have shown that postoperative PTH is not a reliable marker in predicting postoperative hypocalcemia in patients with vitamin D deficiency." (PMID 28955671, 2017). "Moreover, even in toddlers with raised serum PTH levels, hypocalcemia and seizures were found to be rare, with delayed clinical expression." (PMID 27467896, 2016). "He had hypocalcemia, hyperphosphatemia, and elevated Parathyroid Hormone levels." (PMID 27703483, 2016). "He had hypocalcemia, hyperphosphatemia, and elevated PTH with normal vitamin D levels." (PMID 27703483, 2016). "FGF23 is upregulated by PTH and 1,25(OH)2D and downregulated by hypocalcemia." (PMID 27775655, 2016). "The editorial selected posed the question of whether increases in PTH levels and hypocalcemia during bisphosphonate treatment in patients with metastatic breast cancer could be predisposing factors to osteonecrosis of the jaw." (PMID 26827062, 2016). "Intact PTH is typically low but can be inappropriately normal for the degree of hypocalcemia." (PMID 28138323, 2016).